CA12 (carbonic anhydrase 12)
Description:
Reversible hydration of carbon dioxide.
Synonyms: CA-XII; HsT18816; CAXII; T18816
Tractability: Small molecule: an approved drug acts on it; a structure with a bound ligand is known; a high-quality ligand is known; it has a high-quality binding pocket; it belongs to a druggable protein family. Antibody: UniProt places it where antibodies can reach, with high confidence; its Gene Ontology location is reachable by antibodies, with high confidence; UniProt predicts a signal peptide or a membrane-spanning region. PROTAC: ubiquitination databases record sites on it; its protein half-life has been measured; a small molecule that binds it is known.
Target class: Enzyme; Lyase
Chemical probes: ASTRAGALIN, PD081301, PD081488, PD081510, PD082017, PD083011, PD083109, PD084337, PD085374
Gene: Protein-coding gene on chromosome 15 (63,321,378 to 63,382,027, reverse strand). Ensembl gene ENSG00000074410.
Subcellular location: Membrane; Cell membrane
Pathways (Reactome):
Metabolism: Reversible hydration of carbon dioxide
Gene Ontology:
Molecular function: carbonate dehydratase activity; zinc ion binding
Biological process: chloride ion homeostasis; estrous cycle
Cellular component: plasma membrane; membrane; apical plasma membrane; basolateral plasma membrane
Genetic constraint (gnomAD): Loss-of-function variants: 31 observed, 43.21 expected, observed/expected ratio (o/e) 0.72, 90% interval 0.54 to 0.97. The upper end of that interval is the gene's LOEUF score, 0.97, which puts it in group 4 of 6, group 1 being the genes least tolerant of losing a copy. Missense variants: 424 observed, 450.5 expected, observed/expected ratio (o/e) 0.94, 90% interval 0.87 to 1.02. Synonymous variants: 201 observed, 190.94 expected, observed/expected ratio (o/e) 1.05, 90% interval 0.94 to 1.18.
Homologues: Orthologues: chimpanzee CA12 (99% identical), macaque CA12 (84% identical), dog CA12 (82% identical), mouse Car12 (82% identical), pig CA12 (81% identical), rat Car12 (81% identical), guinea pig CA12 (76% identical), rabbit CA12 (66% identical), tropical clawed frog ca12 (47% identical), zebrafish ca12 (31% identical), Caenorhabditis elegans cah-5 (26% identical), Drosophila melanogaster CAH8 (25% identical), and 12 more. Paralogues in human: CA14 (39% identical), CA9 (35% identical), CA6 (31% identical), CA7 (28% identical), CA1 (27% identical), CA4 (27% identical), CA13 (27% identical), CA2 (26% identical), CA8 (25% identical), CA3 (25% identical), CA5A (24% identical), CA5B (24% identical), and 2 more.
Diseases named in the same sentence as CA12 in open-access papers:
CA12 is named in the same sentence as 68 diseases in open-access papers, as found by Europe PMC text mining. Sharing a sentence is not in itself a finding about the gene and the disease. The quoted sentences say what the papers report.
breast carcinoma (44 papers, 2003 to 2025). "CA12 is overexpressed in breast tumor tissues than normal breast tissues and is significantly associated with breast cancer prognosis." (PMID 34930261, 2021). "Nevertheless, higher CA12 expression was associated with significantly better prognosis of breast cancer patients for DFS and OS." (PMID 32432037, 2020). "CA12 encodes a carbonic anhydrase whose expression is regulated by estrogens in MCF-7 and T-47D breast cancer cell lines." (PMID 36358871, 2022). "This study aimed to investigate the effects of carbonic anhydrase 12 (CA12)-siRNA on the paclitaxel sensitivity of breast cancer cells." (PMID 34696661, 2021). "In the six human breast cancer cell lines with different molecular subtypes, the influence of hypoxia (0.1% O2) on CA 9/CA IX and CA 12/CA XII mRNA and protein expression levels was investigated." (PMID 34445506, 2021). "Although the importance of CA XII for the prognosis of cancer patients is controversial, high CA 12/CA XII expression is associated with better disease-free survival of breast cancer patients." (PMID 34445506, 2021). "Li and his colleagues indicated that carbonic anhydrase 12 (CA12), a transmembrane protease, showed significantly higher expression in breast cancer tissues than in para-tumor tissues." (PMID 32432037, 2020). "For example, CA12, a highly correlated gene with estrogen receptor α (ERα), is robustly regulated by estrogen via ERα in breast cancer cells, and this regulation involves a distal estrogen-responsive enhancer region." (PMID 22369133, 2011). "Next, we compared levels of CA12 RNA (RT-qPCR) and CAXII protein (western analysis) in cell lines corresponding to different breast cancer subtypes using a polyclonal antibody previously validated for CAXII detection in western and immunohistochemistry analyses." (PMID 36358871, 2022). "Although CA12 is regulated in breast cancer cells by other transcription factors (TFs) such as AP2γ and by hypoxia, albeit much less than its paralog CA9, we show that its RNA expression levels are amongst the most highly correlated with those of the ESR1 gene in several transcriptome datasets." (PMID 36358871, 2022). "Analysis of transcript co-regulation in our samples showed that additional genes are expressed in parallel with GATA3, including those coding for carbonic anhydrase XII (CA12), cyclin D1 (CCND1) or hepsin (HPN), all of which have been associated with breast cancer." (PMID 24205108, 2013). "On the other hand, carbonic anhydrases, namely CA12, CA2, and CA1, were the major breast cancer protein targets interconnected to the identified metabolites according to their degree of involvement." (PMID 39482666, 2024). "Most markedly CA9/Car9 and CA12/Car12 are upregulated, whereas CA4/Car4 is downregulated in human as well as murine breast cancer tissue." (PMID 37098526, 2023). "Therefore, we hypothesized that CA-12 might contribute to the resistance of breast cancer." (PMID 34696661, 2021). "Compared to female breast cancer, IGF1-R and carbonic anhydrase 12 (CAXII) were more frequently and CD44v6, MET and FGFR2 less frequently expressed in male breast cancer." (PMID 23308200, 2013). "Next, to examine whether CA12 contributes to LINC02568 function in cellular pH control and malignant phenotypes of ER+ breast cancer cell, we performed rescue experiments in which CA12 was introduced when LINC02568 was knocked down in MCF7 cells." (PMID 37404090, 2023). "Taken together, our observation indicated that LINC02568 serves as a potential therapeutic target in ER+ breast cancer, such that ASO targeting LINC02568 alone or in combination with endocrine therapy drugs or CA12 inhibitor is potent in inhibiting ER+ breast tumor growth." (PMID 37404090, 2023). "To investigate whether CA12 protein expression in normal breast cell, breast cancer cells, and PTX resistant breast cancer, we measured CA12 protein levels by western blotting." (PMID 34696661, 2021).
breast carcinoma (continued). "The FOXA1 gene, which opposes SOX10 expression, cooperates with ER1 to maintain luminal identity in breast cancer, whereas GATA3, XBP1, and CA12 showing a negative correlation with SOX10, also cooperate in ER1 signaling." (PMID 36496864, 2022).
breast tumors (10 papers, 2003 to 2024). "Based on these factors, LRRC15, EFNA3, TSPAN13, and CA12 were identified as transcripts with higher expression and prevalence levels in breast tumors, with low expressions in most of the control tissues." (PMID 38611080, 2024). "Taken together, our data indicated that CA-12 was overexpressed in PTX resistant breast tumors." (PMID 34696661, 2021).
colon carcinoma (9 papers, 2003 to 2022). "Carbonic anhydrase 12 (CA12) is a transmembrane protein, which was found to be differentially expressed in colon cancer and a useful clinical tool in discriminating the prognosis of cervical cancer." (PMID 35847888, 2022). "In detail, in the colon carcinoma cell line LS174Tr, knockdown of CA 9 revealed up-regulation of CA 12, and increased CA XII expression was observed from the immunohistochemical results of tumor sections of mice injected with CA 9-diminished cells in vivo." (PMID 34445506, 2021). "In accordance with our data, simultaneous knockdown of CA 9 and CA 12 in colon carcinoma cells resulted in stronger radiosensitization than single knockdown of either CA 9 or CA 12, which is possibly due to a rescue mechanism between CA IX and CA XII." (PMID 34445506, 2021).
glioblastoma (8 papers, 2014 to 2021). The most malignant astrocytic tumor (WHO grade IV). "Because CA12 is expressed at low levels in normal brain, it is a interesting therapeutic target for the group of CA12-positive glioblastomas." (PMID 31747973, 2019).
hepatocellular carcinoma (3 papers, 2022 to 2025). A malignant tumor that arises from hepatocytes. "Here, we found that levels of carbonic anhydrase XII (CA12) expression were significantly and selectively upregulated on macrophages in human hepatocellular carcinoma (HCC)." (PMID 35362480, 2022).
liver cancer (3 papers, 2023 to 2025). An epithelial or non-epithelial malignant neoplasm that arises from the liver. "Meanwhile, scientist demonstrated that aberrant aerobic glycolysis in liver cancer cells can induce carbonic anhydrase XII (CA12) in tumor-associated macrophages (TAMs), thereby promoting the M2 TAM phenotype and facilitating tumor growth and metastasis." (PMID 39227970, 2024).
renal carcinoma (3 papers, 2014 to 2021). A carcinoma arising from the epithelium of the renal parenchyma or the renal pelvis. "The gene encoding CA XII, CA12, is a target of hypoxia-inducible factor 1 (HIF-1), and a common feature of many renal carcinomas is mutations in the von Hippel-Lindau (VHL) tumor suppressor gene, a regulator of HIF-1." (PMID 35582034, 2021).
pancreatic cancer (2 papers, 2023 to 2024). "In Gao’s et.al risk prediction model, CA12 (Carbonic anhydrase 12) showed a higher expression level in the high-risk group, and similar to our findings, was a risk factor for prognosis in pancreatic cancer." (PMID 37198621, 2023). "Another study revealed that pancreatic cancer cells with low expression of carbonic anhydrase 12 (CA12) can regulate the oxidative stress response through the NF-κB signaling pathway, making the cancer cells more susceptible to Auranofin treatment." (PMID 39867576, 2024).
thyroid cancer (2 papers, 2019 to 2025). "CD26, secretogranin V (SCG5) and carbonic anhydrase XII (CA12) are a three-gene signature that can distinguish malignant thyroid cancers, and is useful for preoperative diagnosis of thyroid cancer." (PMID 31194830, 2019).
colorectal tumors (1 paper, 2023). "Thus, CA9 and CA12 seem to have no complementary roles in colorectal tumors but rather can also occur in a co-expressed manner." (PMID 36982873, 2023).
degenerative disc disease (1 paper, 2020). "Therefore, genetic or pharmacological modulation of IGF-1/PI3K/CREB/CA12 activity may be a promising therapeutic approach to degenerative disc disease and a novel model for research focusing on IVDD and endplate degeneration." (PMID 33178705, 2020).
esophageal squamous cell carcinoma (1 paper, 2018). Esophageal squamous cell carcinoma (ESCC) is a type of esophageal carcinoma (EC) that can affect any part of the esophagus, but is usually located in the upper or middle third. "We previously investigated the functions of ion transporters, water channels, and pHi regulators including AE1, NHE1, and CA12 in esophageal squamous cell carcinoma (ESCC)." (PMID 29899837, 2018).
growth failure (1 paper, 2023). "Another possible cause of recurrent hyponatremia, growth failure, and high sweat chloride is dysfunction carbonic anhydrase 12 (CA12), which is a protein localized in the apical of the bronchiolar epithelia and basolateral membrane of the reabsorption duct of sweat glands." (PMID 37554905, 2023).
Obesity (1 paper, 2022). Accumulation of substantial excess body fat. "Among them, the upregulated gene BCL2A1 is common in CVD, HTN, obesity, and aging; RNF144B and PTGIS are common in HCL, obesity, aging, and CVD; G0S2, CXCL1, ACKR3, and PTPRD are found in HTN, aging, and CVD; TGFB2, CA12, and MSR1 are familiar in obesity, aging, and CVD." (PMID 36035865, 2022).
tumor (115 papers, 2003 to 2026). "Given the elevated expressions in different cancer types, CA9 and CA12 are considered as tumor-associated CAs, and thus are most studied CA isoforms in respect to tumor settings." (PMID 38530845, 2024). "Consistently, the accumulation of CA12+ macrophages in tumor tissues was associated with increased tumor metastatic potential and reduced survival of patients with HCC." (PMID 35362480, 2022). "The expression of carbonic anhydrase XII (CA12) gene which encodes a zinc metalloenzyme participating in acidification of tumor microenvironment, demonstrates correlation with estrogen receptor alpha in human BC." (PMID 31534839, 2019). "CA12 also tends to be expressed in the normal tissue counterparts of several solid tumors, even though CA12 is known as one of the tumor-associated carbonic anhydrases." (PMID 21040567, 2010). "Recently, we identified the tumour-associated carbonic anhydrases (CA), CA9 and CA12 as hypoxia-inducible in tumour cell lines." (PMID 12671706, 2003). "CA12 is one of the tumor-associated antigens known to be overexpressed under hypoxic conditions." (PMID 21040567, 2010). "CA12 belongs to the protein family of membrane‐associated CAs, which have been shown to be involved in creating and maintaining the pH difference between the intra‐ and extracellular spaces in the hypoxic tumor microenvironment, thereby promoting tumor cell growth and metastasis." (PMID 37404090, 2023). "In addition, the loss of radioresistant hypoxic cells due to CA9/CA12 silencing could contribute to the reduction of tumor growth in combination with their radio-sensitivity due to decreased pHi regulation." (PMID 23316475, 2012). "As a result, we identified four membrane proteins—LRRC15, EFNA3, TSPAN13, and CA12—that demonstrated high expressions in BC tissues compared to adjacent non-tumor breast tissues and other healthy samples, with a few exceptions." (PMID 38611080, 2024). "Given their essential roles in regulating pH balance and tumor association, substantial efforts have been made to generate specific CA inhibitors (CAi) against two membrane associated CA isoforms—CA9 and CA12 as anticancer therapy for the last two decades." (PMID 38530845, 2024). "CA12 mediates the survival of macrophages in acidic tumor microenvironments and stimulates TAMs to produce large amounts of CCL8, which enhances EMT in cancer cells." (PMID 39516356, 2024). "Transient glycolytic activation of peritumoral monocytes in hepatocellular carcinoma was found to induce sustained expression of carbonic anhydrase XII (CA12) on tumor-infiltrating macrophages via autocrine cytokines and the HIF1α pathway." (PMID 39516356, 2024). "In contrast, CA12 overexpression exhibited the opposite effects, further strengthening the critical role of CA12 in controlling tumor‐specific pH homeostasis and promoting the malignant phenotypes of MCF7 cells." (PMID 37404090, 2023). "Among the 15 isoforms known in humans, 2 cell-surface CA isoforms, namely, CA9 (or CA IX, almost exclusively associated with tumors) and CA12 (or CA XII, upregulated in some tumor types), are involved in tumorigenesis." (PMID 35362480, 2022). "CA12, a single transmembrane protease containing zinc metal, can catalyze a reversible reaction of carbon dioxide hydration and dehydration in tumor tissues, thereby regulating the pH of the extracellular microenvironment." (PMID 34696661, 2021). "Narasimha Rao Uda etc., found that blocking the enzymatic activity of Carbonic Anhydrase 12 would decrease tumor proliferation, and CA12 would be a novel therapy target for CA12-positive tumor." (PMID 34930261, 2021). "Among the members of the CA isozyme family, CA2, CA9, and CA12 have been shown to be related to tumor genesis." (PMID 24959000, 2014). "Overexpression of CA12 is also observed in von Hippel-Lindau(VHL)-defective tumor cells with CA9, and is believed to contribute in an acid extracellular PH in malignant tumors." (PMID 21040567, 2010).
tumor (continued). "Recently, we extended the range of HIF-1 target genes by identifying the two tumour-associated transmembrane carbonic anhydrases (CA) CA9 and CA12 as upregulated by hypoxia in a range of epithelial cancer cell lines." (PMID 12671706, 2003). "At 10 μM, rA12 exhibited similar tumor lysis and pro-apoptosis effect to cA12." (PMID 35761329, 2022). "Overexpression of CAXII (CA12) has been found in hypoxia—the oxygen deprivation of cancer cells due to a combination of poor tumor vascularization and high proliferation rate, despite the fact that hypoxia response elements (HREs) essentially lack in the 5’-upstream genomic region of CAXII gene." (PMID 36424626, 2022). "To explore whether CA12 facilitates tumor metastasis by regulating the production of CCL8 in monocytes, we treated CD14+ cells from healthy donors with HepG2 TSN in the presence or absence of the glycolysis inhibitor 2DG, CA12 inhibitor, or siCA12." (PMID 35362480, 2022). "Consequently, the greatest reduction in tumour volume was achieved through silencing both ca9 and ca12 genes." (PMID 32570870, 2020). "Finally, LS174Tr tumor progression was strongly decreased when ca9/ca12 silencing was combined with irradiation in vivo." (PMID 23316475, 2012). "We suggest that CA12 activity is a previously unappreciated mechanism regulating the accumulation and functions of macrophages in tumor microenvironments and therefore represents a selective vulnerability that could be exploited in future designs for antitumor immunotherapeutic strategies." (PMID 35362480, 2022). "Among the 991 BC tumor samples, GATA3 had the highest frequency of somatic SNVs, accounting for 13%; followed by FOXA1, accounting for 3%; AGR2, CA12, CEP55, CDC20, TBC1D9, and MELK had very few somatic SNVs." (PMID 39440050, 2024). "To investigate CA9/CA12 expression depending on the molecular subtype, we employed the same CRC datasets and applied the CMScaller to classify tumor samples according to the CMS classification system." (PMID 36982873, 2023). "The levels of GLUT1 and CA12 expression were positively correlated both in in vitro tumor-exposed monocytes and in their HCC tumor–purified counterparts." (PMID 35362480, 2022). "In vivo experiments showed that CA9 gene silencing alone led to a 40% reduction in xenograft tumour volume, and the silencing of both CA9 and CA12 resulted in an 85% reduction in tumour volume." (PMID 20398423, 2010). "To explore the possible role of CA12 in tumor-associated monocytes and macrophages, we treated peripheral CD14+ cells with HepG2 TSN in the presence of negative control siRNA (siNC), CA12 siRNA (siCA12)." (PMID 35362480, 2022). "CA12 is a transmembrane, extracellular enzyme and member of a family of zinc metalloenzymes that catalyze the reversible hydration of CO2 to form bicarbonate, regulating the microenvironment acidity and tumor malignant phenotype." (PMID 35134148, 2020). "TMEM108 and C3orf47 were positively correlated with tumor grade and eight genes, including LAD1, TIF1, FGF11, carbonic anhydrase 12 (CA12), G protein subunit α15 (GNA15), junction plakoglobin (JUP), plakophilin 1 (PKP1) and PPARD, were negatively correlated with the tumor grade of ESCC patients." (PMID 28904855, 2017). "Although TSCC tumor samples and TSCC15 cells also express CA2 and CA12, our in-house RNA-seq data showed that the expression levels of CA2 and CA12 were not altered when the expression of 887S or 887L was modulated." (PMID 34493285, 2021). "By comparing genes differentially expressed by monocytes purified from tumor and paired nontumor liver tissues of HCC patients, we found that, among all αCA family genes, CA12 was the most markedly upregulated gene in tumor-infiltrating monocytes compared with those from nontumor liver tissues." (PMID 35362480, 2022).